TGFBR2 (transforming growth factor beta receptor 2)
Diseases named in the same sentence as TGFBR2 in open-access papers (continued):
Sharing a sentence is not in itself a finding about the gene and the disease.
oral cancer (3 papers, 2016 to 2023). "By translating the most significantly expressed gene matrix into clinical datasets of oral cancer tissues, we showed that the summed expression of FN1, TGFB2, TGFBR2, and TGFBI, dubbed the CAF index, is a poor indicator of overall survival for oral cancer (n=40) and the PANCAN (n=9,356) cohorts." (PMID 34869001, 2021).
osteoporosis (3 papers, 2018 to 2022). A condition of reduced bone mass, with decreased cortical thickness and a decrease in the number and size of the trabeculae of cancellous bone (but normal chemical composition), resulting in increased fracture incidence. "Has-miR-133a-3p was involved in osteoclast formation, differentiation, apoptosis, and resorption, showing great promise as a potential therapeutic target for biomarkers and osteoporosis, and was found to regulate TGFBR2 and FHL1 expression in this study." (PMID 31737663, 2019). "Such clustering results are interesting as TGFBR1, TGFBR2 and SMAD3 formed a cluster that showed enhanced expression in primary osteoporosis." (PMID 36443839, 2022).
ovarian tumors (3 papers, 2012 to 2021). "We next demonstrated that TGFBR2 knockout NK cells kill SK-OV-3 ovarian tumor spheroids more efficiently than control unedited NK cells in the presence of 10 ng/mL TGF-β at an effector to target ratio of 10:1." (PMID 34162850, 2021).
Shprintzen-Goldberg syndrome (3 papers, 2015 to 2025). Shprintzen-Goldberg syndrome (SGS) is a very rare genetic disorder characterized by craniosynostosis, craniofacial and skeletal abnormalities, marfanoid habitus, cardiac anomalies, neurological abnormalities, and intellectual disability. "Moreover, Shprintzen-Goldberg syndrome (SGS), a disorder involving craniosynostosis, intellectual disability, and skeletal abnormalities, has been associated with mutations in TGFBR2, though it presents with distinct craniofacial and neurological features compared to LDS." (PMID 40612107, 2025).
tendinopathy (3 papers, 2016 to 2022). "Systemic inhibition of TGF‐β activity by injection of a TGF‐β neutralizing antibody or knockout of the TGF‐β type 2 receptor gene (Tgfbr2) in tenocytes efficiently blocked progression of tendinopathy." (PMID 35166070, 2022). "Inducible knockout of the TGF‐β type 2 receptor gene (Tgfbr2) in tenocytes inhibited tendinopathy progression in mice." (PMID 35166070, 2022). "Although we demonstrate downregulation of TGFβ signalling mediators with established tendon disease, TGFBR2 mRNA was upregulated in tendon tears." (PMID 26883016, 2016). "Similarly, no significant modulation of TGFR2 (TGFBR2) was observed in our in vitro model, although knockout of the TGFBR2 gene in tenocytes has been shown to attenuate development of tendinopathy." (PMID 36499497, 2022).
thyroid tumours (3 papers, 1999 to 2024). "Loss of TGFBR2 expression in thyroid tumors was already reported in the 90's using Northern blot and in-situ hybridization analysis." (PMID 33905626, 2021).
Allergy (2 papers, 2016 to 2023). An allergy is an immune response or reaction to substances that are usually not harmful. "The levels of FS (Follistatin), Erb-B2 receptor tyrosine kinase 2 (ERBB2), TGFR2 (transforming growth factor beta receptor 2), MSLN (mesothelin) and TM (thrombomodulin) were influenced by Benzodiazepines and PRS27 (serine protease 27) by allergy drugs." (PMID 37667404, 2023).
arachnodactyly (2 papers, 2024 to 2025). "Genetic variants in genes including TGFBR1, TGFBR2, TGFB2, TGFB3, SMAD2, and SMAD3 result in Loeys–Dietz syndrome and are reported to cause Marfan-like phenotypes and variants in FBN2 and COL3A1 result in congenital contractural arachnodactyly and Ehlers–Danlos syndrome type IV." (PMID 38791509, 2024).
Bicuspid aortic valve (2 papers, 2013 to 2024). The presence of an aortic valve with two instead of the normal three cusps (flaps). "The purpose of our study was to investigate the potential contribution of germline mutations in NOTCH1, GATA5 and TGFBR1 and TGFBR2 genes in a cohort of Italian patients with familial Bicuspid Aortic Valve (BAV)." (PMID 23578328, 2013).
bladder tumor (2 papers, 2016 to 2019). "In conclusion, this study demonstrated that genetic deletion of Tgfbr2 or treatment of Tgfbr1 small molecule inhibitor LY364947 led to decrease of bladder tumor invasion and progression." (PMID 27378170, 2016).
cardiac failure (2 papers, 2013 to 2021). "TGF-β and related signalling pathways also play an important role in the process of heart failure.TGFBR2 is a type II receptor of TGF-β, which contains an intracellular serine/threonine kinase domain." (PMID 34658880, 2021). "Our results showed that NPs loaded with miR-30b-5p could regulate the expression of certain inflammatory factors by lowering TGFBR2, and then achieve the purpose of treating heart failure." (PMID 34658880, 2021).
Chagas disease (2 papers, 2022 to 2023). A parasitic infection caused by Trypanosoma cruzi. "Furthermore, the same network identified KEGG terms related with protozoan infection, such as malaria, Chagas disease and leishmaniosis, pointing to a convergent set of genes (TGFB1, TGFB3, and TGFBR2) related with those infections and BV." (PMID 36985125, 2023). "CircRNA_100086 could regulate the expression of MAPK1 and TGFBR2 by sponging miR-509-3p to participate in the pathways of hsa:04,350: TGF-beta signalling pathway, hsa04068: FoxO signalling pathway, hsa05142: Chagas disease (American trypanosomiasis) and hsa:04,380: Osteoclast differentiation." (PMID 35840955, 2022).
cholangiocarcinoma (2 papers, 2017 to 2026). A carcinoma that arises from the intrahepatic biliary tree (intrahepatic cholangiocarcinoma) or from the junction, or adjacent to the junction, of the right and left hepatic ducts (hilar cholangiocarcinoma). "Surprisingly, both hepatocyte- and cholangiocyte-specific deletion of PTEN and TGFBR2 promoted the development of cholangiocarcinoma." (PMID 41109667, 2026).
chronic myeloid leukemia (2 papers, 2014 to 2016). "The significantly enriched pathways included chemokine signaling pathway (which involved CCL2), focal adhesion (which involved THBS1 and THBS2), TGF-beta signaling pathway (which involved THBS1, THBS2, SMAD5, and SMAD6) and chronic myeloid leukemia (which involved TGFBR2 and CCND1)." (PMID 27716259, 2016).
colorectal adenocarcinoma (2 papers, 2020 to 2025). The most common type of colorectal carcinoma. "Three of the twenty-one genes predicted to be affected by these miRNAs—SMAD2, SMAD4, and TGFBR2—were shared between pathways related to colorectal adenocarcinoma (COAD) and TGF-β signaling." (PMID 40868288, 2025). "Meanwhile, another study found the relation between expression of CEA (CEACAM5) gene and TGF-β pathway genes (TGFBR1, TGFBR2, and SMAD3) in colorectal adenocarcinoma cells." (PMID 33123542, 2020).
COVID-19 (2 papers, 2021 to 2025). A disease caused by infection with severe acute respiratory syndrome coronavirus 2. "The significant upregulation of TGFBR2 in vascular ECs of COVID-19 patients suggests that TGFβ signaling may play a role in the endothelial response to viral infection." (PMID 41159753, 2025).
diffuse large B-cell lymphoma (2 papers, 2016 to 2022). "TGFBR2 is a component of gene expression signatures of diffuse large B-cell lymphoma (DLBC) subclasses, with GC-like DLBCL showing a relative decrease in TGFBR2 expression, whereas activated B-cell (ABC)-DLBCL shows relative increase." (PMID 35406544, 2022).
dyslipidemia (2 papers, 2017 to 2023). "The GMDR analysis confirmed that TGFBR2 rs4522809, smoking, dyslipidemia, and MLL3 rs1137721 likely work together to affect the risk of Stanford type B AD." (PMID 37226099, 2023).
Ewing sarcoma (2 papers, 2012 to 2022). A small round cell tumor that lacks morphologic, immunohistochemical, and electron microscopic evidence of neuroectodermal differentiation. "The expression of the selected target genes in Ewing’s sarcoma (CAV1, NR0B1, IGFBP3 and TGFBR2), together with the expression of HIST1H4L, KCNN2, ECRG4 and LDOC1, was then validated in an independent series of PCa with and without ETS gene fusions, as well as in a series of ESFT and ARMS." (PMID 23185447, 2012).
Hernia (2 papers, 2020 to 2025). "Pgr+ fibroblasts likely play a central role in this process of hernia development, as they are upregulated in EP LAM and have increased expression of Tgfb2, Tgfbr1, and Tgfbr2." (PMID 40504614, 2025). "Expression levels of both TGFBR2 and TGFB2 were significantly increased in herniated LAM tissue compared with matched healthy LAM tissue, suggesting that increased TGF-β signaling in LAM tissue may contribute to hernia development in humans." (PMID 40504614, 2025).
Hodgkin disease (2 papers, 2022). "Early research using EBV-specific cytotoxic T-cell lymphocytes used for the treatment of EBV-positive Hodgkin disease show that modification through the expression of a dominant-negative TGFBR2 resisted the immunosuppressive effects of TGFB and enhanced cytotoxicity." (PMID 35406544, 2022).
hyperglycaemia (2 papers, 2022 to 2025). "Interestingly, astrocyte markers (CD44, KCNJ10, and TGFBR2) were upregulated under hyperglycaemia in the NGS dataset." (PMID 41419458, 2025). "However, astrocyte markers, including CD44, KCNJ10, TGFBR2, GFAP, and S100β, were upregulated under hyperglycaemia, as shown by both NGS transcriptomic analysis and immunostaining." (PMID 41419458, 2025).
injury (2 papers, 2016 to 2025). Damage inflicted on the body as the direct or indirect result of an external force, with or without disruption of structural continuity. "This study is the first to use multi-species data to explore TGFBR2 expression in fibroblasts from patients with post-radiation skin injury." (PMID 41050697, 2025). "The results suggest that TGFBR2 is a key gene in post-radiation skin injury, increasing the likelihood of our findings." (PMID 41050697, 2025).
Insulin resistance (2 papers, 2017 to 2024). Increased resistance towards insulin, that is, diminished effectiveness of insulin in reducing blood glucose levels. "An animal study suggested that the deletion of the Tgfbr2 gene in hepatocytes influences systemic insulin resistance and body weight gain in mice during the development of nonalcoholic fatty liver disease, which is the hepatic manifestation of MetS12." (PMID 29051557, 2017).
intracerebral hemorrhage (2 papers, 2020 to 2024). A cerebrovascular disorder characterized by bleeding into one or both cerebral hemispheres including the basal ganglia and the cerebral cortex. "Endothelial TGF-β signaling has been shown to be essential for cerebral angiogenesis, since Tgfbr2 or Alk5 gene knockout blood vessels fail to invade into the neuroepithelial layers and exhibit intracerebral hemorrhage." (PMID 33072751, 2020). "Tgfbr2 silencing in forebrain-derived neural progenitors and neural cells impedes EC migration and sprouting, decreases vessel density and branching via altered secretion of pro- and anti-angiogenic factors, thereby leading to intracerebral hemorrhage in the telencephalon." (PMID 33072751, 2020).
Loeys Dietz syndrome type 2 (2 papers, 2010 to 2023). "Variants in TGFBR2 have been associated with Loeys Dietz syndrome type 2." (PMID 37228816, 2023).
lupus (2 papers, 2022 to 2025). "Specifically, ligand–receptor pairs such as Thy1-(Itgam+Itgb2), Mif-(Cd74+Cxcr4), Tgfb1-(Tgfbr1+Tgfbr2), and Pecam1-Pecam1 showed higher mean expression levels in lupus mice than in DHA-treated mice." (PMID 40728997, 2025). "Lower plasma level of TGF-β1 in LN patients and lower expression of TGFBR2 in lupus mice kidney futher indicate the involvement of TGF-β in LN." (PMID 36275661, 2022). "Lower plasma level of TGF-β1 (P<0.05) in LN patients and lower expression of transforming growth factor beta receptor 2 in lupus mice kidney (P<0.05) futher indicate the involvement of TGF-β in LN." (PMID 36275661, 2022).
metastatic carcinoma (2 papers, 2018 to 2024). A carcinoma which has spread from the original site of growth to another anatomic site. "Disruption of TGFß signaling either by Smad4 or Tgfbr2 deletion in the background of a prostate specific tumor initiating mutation results in rapid progression to invasive and metastatic cancer in mouse models." (PMID 29782499, 2018). "Deletion of Pten and Tgfbr2 specifically from luminal cells also causes a rapid onset of invasive and metastatic cancer that is accompanied by a transition to a less differentiated cell type." (PMID 29782499, 2018). "To better model the primarily luminal phenotype of human CaP we mutated Pten and Tgfbr2 specifically in luminal cells, and found that these tumors also progress to invasive and metastatic cancer." (PMID 29782499, 2018). "When combined with a conditional Tgfbr2 allele we observed a rapid progression to invasive and metastatic cancer, which was not seen in Pten single mutants, even at advanced age." (PMID 29782499, 2018). "However, deletion of Tgfbr2 and Pten specifically in luminal cells resulted in metastatic cancer and extensive de-differentiation to an intermediate cell type expressing both basal and luminal markers." (PMID 29782499, 2018).
Patent ductus arteriosus (2 papers, 2018 to 2023). In utero, the ductus arteriosus (DA) serves to divert ventricular output away from the lungs and toward the placenta by connecting the main pulmonary artery to the descending aorta. "Meanwhile, transforming growth factor beta (TGF-β) receptor type 1 (TGFBR1) and TGFBR2 gene alterations are linked to patent ductus arteriosus." (PMID 36344649, 2023).
pituitary tumor (2 papers, 2019 to 2020). A benign or malignant neoplasm affecting the pituitary gland. "LncRNA SNHG1 activated the TGFBR2/SMAD3 and RAB11A/Wnt/β-catenin pathways to promote the progression of pituitary tumors by sponging miR-302/372/373/520 in pituitary tumor cells." (PMID 32192168, 2020).
preeclampsia (2 papers, 2013 to 2018). Preeclampsia is a hypertensive disorder of pregnancy that is characterized by new-onset hypertension with proteinuria presenting after 20 weeks of gestation, and depending on mild or severe forms may initially present with severe headache, visual disturbances, and hyperreflexia. "Our exploratory subgroup findings suggest that certain tSNPs in two ENG pathway candidate genes were also found to be significantly associated with preeclampsia in the Latina cohort, ALK1(rs706819, 3′ UTR variant) and TGFBR2(rs984394, intronic)." (PMID 29580923, 2018). "Our results further suggest that the pathway’s involvement in preeclampsia differs in whites and blacks, with ENG and TGFBR2 being associated in whites and TGFβ1, TGFβR1, and TGFβR2 being associated in blacks." (PMID 23548068, 2013).
premature ovarian failure (2 papers, 2022 to 2026). "Interestingly, several commonly upregulated genes were observed across cell types, including PTEN, TGFBR2, ATG7, and ESR1, which are implicated in primary ovarian insufficiency." (PMID 41243550, 2026).
prostate (2 papers, 2012 to 2017). "However, the expression of CAV1, IGFBP3 and TGFBR2 is decreased in PCa in general, suggesting a role in prostate carcinogenesis." (PMID 23185447, 2012).
prostate intraepithelial neoplasia (2 papers, 2013 to 2018). A neoplastic proliferation of the epithelial cells that line the acini and the ducts of the prostate gland. "Furthermore, TGF-β/Wnt signaling following the knockout of TGFBR2 enabled the prostatic intraepithelial neoplasia lesions to progress to adenocarcinoma and even facilitated the epithelia to become resistant to androgen ablation." (PMID 29699590, 2018).
pulmonary arterial hypertension (2 papers, 2023 to 2025). Pulmonary arterial hypertension (PAH) is a group of diseases characterized by mean pulmonary artery pressure >20 mmHg and elevated pulmonary arterial resistance leading to right heart failure. "Studies show that in pulmonary hypertension models, TGFBR2’s transcriptional activation under hypoxia is suppressed, and the interaction between its promoter and distal enhancer is weakened." (PMID 40427283, 2025).
retinitis pigmentosa (2 papers, 2021 to 2025). Retinitis pigmentosa (RP) is an inherited retinal dystrophy leading to progressive loss of the photoreceptors and retinal pigment epithelium and resulting in blindness usually after several decades. "Previous studies confirmed that overexpression of TGFB1 in the cones can reduce the cone degeneration caused by retinitis pigmentosa through microglia and ablation of TGFBR2 in retinal microglia lead to the microglia activation and promote the pathological microglial gene expression profile." (PMID 34434927, 2021). "Even more interesting, we found that TGFBR2 is upregulated in neurons and Müller cells in VPP mice, a genetic mouse model for retinitis pigmentosa." (PMID 40817252, 2025).
retinoblastoma (2 papers, 2015 to 2021). A malignant tumor that originates in the nuclear layer of the retina. "In contrast, transcriptional repression of TGFBR2 was reported in retinoblastoma and hematopoietic malignancies." (PMID 27462425, 2015).
scoliosis (2 papers, 2014 to 2025). A congenital or acquired spinal deformity characterized by lateral curvature of the spine. "Scoliosis can be found in 46% of patients with Loeys-Dietz syndrome; a multisystem disease caused by a mutation in the genes encoding TGFBR1 or TGFBR2." (PMID 25313366, 2014). "While cleft palate can be seen in some of these patients (two of the first six TGFBR2 participants reported), the more common clinical characteristics include arterial aneurysm/dissection, skeletal phenotypes such as scoliosis or joint laxity, and craniosynostosis." (PMID 40489498, 2025). "The transcriptional activity of TGF-β2, TGF-β3, and TGFBR2 and the expression profile of TGF-β responsive genes differ in paravertebral muscle transcriptomes depending on the age of scoliosis onset and the side of the scoliotic curve." (PMID 25313366, 2014).
stomach adenocarcinoma (2 papers, 2022 to 2024). "M2 macrophages also showed a preferential expression of TGFBR1 and TGFBR2 genes in colon, lung, and stomach adenocarcinomas based on TCGA database." (PMID 38441961, 2024).
testicular germ cell tumor (2 papers, 2011 to 2018). A germ cell tumor arising from the testis. "There are a number of other miRNAs predicted to target the 3' UTR regions of the type I and type II TGF-β receptors that are expressed in cancer cell lines, including miR-373, which is predicted to target TGFBR2 and has been implicated as an oncogene in testicular germ-cell tumors." (PMID 21401928, 2011).
uremia (2 papers, 2013 to 2016). A clinical syndrome associated with the retention of renal waste products or uremic toxins in the blood. "Smad2 and Smad4, TGFBR2 and other members of the TGF-beta and BMP pathways, among the most highly dysregulated probe sets in uremia, may reflect altered bone metabolism." (PMID 23809614, 2013).
viral infection (2 papers, 2017 to 2025). "Both vascular and lymphatic ECs expressed high levels of the transforming growth factor beta receptor 2 (TGFBR2), suggesting endothelial repair in response to viral infection." (PMID 41159753, 2025).
adenomyosis (1 paper, 2021). The growth of endometrial tissue inside the muscular wall of the uterine corpus. "Notably, some uterine epithelia in Tgfbr2 cKO were mislocated to the myometrial compartment (red asterisk), as resembles adenomyosis previously found in mice with conditional deletion of Tgfbr15." (PMID 33927274, 2021).
adenosquamous carcinoma (1 paper, 2014). A carcinoma composed of malignant glandular cells and malignant squamous cells. "Further comparison of the Pten and Apc models of CaP revealed additional differences, including adenosquamous carcinoma in the Apc;Tgfbr2 mutants that was not seen in the Pten model, and a lack of robust induction of the TGFβ pathway in Apc null prostate." (PMID 24651496, 2014).